S100A9 (S100 calcium binding protein A9)
Diseases named in the same sentence as S100A9 in open-access papers (continued):
Sharing a sentence is not in itself a finding about the gene and the disease.
infection (continued). "Previous studies demonstrated that HV-68 infection alone could induce S100A8/S100A9 in vivo during acute infection and viral latency, which was consistent with increased MDSCs in these infected mice." (PMID 22946998, 2012). "Dissemination of E. coli from the uropathogenic tract to the circulation was also undistinguishable in WT and S100A9 KO mice 24 and 48 hours after infection with 4.5×108 CFU (number of positive blood cultures; WT vs. S100A9 KO mice, t = 24: 1/7 vs. 0/8, P = 0.27 and t = 48: 0/6 vs. 1/7, P = 0.34)." (PMID 20976233, 2010). "Dissemination of E. coli from the urinary tract to the circulation was not significantly different between WT and S100A9 KO mice 24 and 48 hours after infection (number of positive blood cultures; WT vs. S100A9 KO mice, t = 24: 0/9 vs. 3/9, P = 0.06 and t = 48: 0/9 vs. 0/9, P = 1.00)." (PMID 20976233, 2010). "As S100A8/A9 might play a role during a less severe infection, we infected WT and S100A9 KO mice with 4.5×108 CFU/mouse." (PMID 20976233, 2010). "While the exact mechanism by which intracellular S100A9 alters mitochondrial homeostasis is unknown, the unique metabolic/immunologic niche of the heart may amplify suicidal NETosis in A9−/− neutrophils during infection." (PMID 34516771, 2021). "Down regulation of S100A9 protein could indicate insufficient immunity stimulated by the infection." (PMID 34372836, 2021). "Hence, S100A8/A9 inhibits the growth of pathogens at infectious sites during the initial phase of infection, allowing time for the recruitment of phagocytes, and then, S100A9 enhances the phagocytic activity of infiltrating leukocytes, accelerating the clearance of pathogens." (PMID 29942307, 2018). "As infection progressed, we detected a robust upregulation of genes encoding cytokines and chemokines (CCL2, CCL3, IL1B, CXCR1, IL1RN) as well as granulocyte associated transcripts (TLRs 1-4, SPI1, S100A8, S100A9, CD177), which correlated with the higher numbers of granulocytes 5 DPI." (PMID 28852031, 2017). "The complement component C8a and S100 proteins, S100a8 and S100a9, were highly differentially abundant in both infected strains, signifying a potential innate immune response and the importance of the complement pathway in defence against macroparasite infection." (PMID 27490109, 2016). "Therefore, reducing S100A9 protein levels may be a mechanism used by M. bovis to evade host immune response and establish infection in young wild boar." (PMID 27027307, 2016). "Although basal transcription of Ifnγ, S100A9 and Lcn2 was similar between mock-infected WT and mock-infected Ifnar1-/- mice, the transcription of Ifnγ and Lcn2 was significantly higher in the ceca of the Ifnar1-/- group, compared to the WT group, after infection with S. Typhimurium alone." (PMID 27149619, 2016). "Many of the selected genes were immune‐related and play a role in the host response against infection, such as BPI, PRSS33, S100A9, CLEC4E, and so on." (PMID 39692191, 2025). "The results of serum sample testing showed that these mAbs specifically identified the proteins S100A8, S100A9 and S100A12 in the serum and were able to evaluate changes in the protein content of S100A8, S100A9, and S100A12 during infection." (PMID 38256103, 2024). "Apart from playing a vital role in human health and diseases, S100A8, S100A9, and S100A12 proteins are closely related to the infection (including bacteria, viruses, and parasites) process in pigs." (PMID 38256103, 2024). "To address the current lack of reliable and timely detection tools for porcine S100A8, S100A9, and S100A12 proteins during the infection process, we generated mAbs specific to these three proteins in this study using hybridoma technology." (PMID 38256103, 2024). "S100A9 KO mice infected with S. pneumoniae ΔPly showed significantly decreased bacterial loads in BALF and lung tissue on day 1 post-infection relative to KO mice challenged with WT S. pneumoniae, with similar BAL neutrophil counts in both groups." (PMID 37467233, 2023).
infection (continued). "Among genes involved in the inflammatory response, S100A9 and SAA1 were upregulated in response to experimental infection in birds from both less-tolerant and more-tolerant populations." (PMID 37294834, 2023). "Infection of S100A9 KO mice with S. pneumoniae led to significantly increased bacterial loads in BALF and lung tissue on days 1 and 2 post-infection when compared to S. pneumoniae-infected WT mice." (PMID 37467233, 2023). "We also found that WT and ATF3 KO mice had a comparable neutrophil number as reflected by s100a9 staining and Ly6G+/CD11b+ population in the FACS analysis in post-infection lung tissue sections." (PMID 35370996, 2022). "Notable abundant genes that also showed highly dynamic expression across the infection course in monocytes include S100A8 and S100A9, which were also up-regulated at Day −2." (PMID 35345453, 2022). "Infection with Salmonella Typhimurium SL1344 led to disordered colonic microbiotas, colonic inflammation through the S100A8/S100A9–NF-κB pathway and potential apoptosis, and translocation of pathogens to parenteral visceral organs in mice." (PMID 35658572, 2022). "Besides, S100A9 contributes to maintain the polarization of M2 TMs, which may impair their ability to resist bacterial in the early stage of infection, but it may also promote the transformation of acute inflammation to chronic and accelerate the repair of tissues in the late stage of infection." (PMID 34764959, 2021). "Among hub genes, most were affected by infection of human or avian influenza viruses such as H7N7, H1N1, H7N9, H3N2, and H5N1; CSF2 and S100A9 were exclusive to SARS-CoV-2 infection." (PMID 34376762, 2021). "Infection with NTHi markedly increased the concentrations of defensin-β2, S100A8 and S100A9 in the BAL of both control and CS-exposed mice." (PMID 33784296, 2021). "Mtb-AG infection significantly upregulated the expression of inflammatory molecules S100A8, S100A9, CRP, IL23, activated NK cell marker (KLRG), and Th-2 type marker, IL10 at 1 week post infection." (PMID 34732811, 2021). "During infection, tissue damage, neutrophil extracellular trap formations (NETs), and cellular necrosis, the levels of S100A8 and S100A9 are increasingly expressed in circulating neutrophils and monocytes and can also be secreted passively." (PMID 32107497, 2020). "The recruitment of neutrophils to the site of infection as well as the induction of Il17f and S100a9, two of the most strongly induced genes by SC5314 on day 1 post-infection, was comparable in both conditions." (PMID 30873177, 2019). "During infection, bacterial effectors can induce S100A8/S100A9 expression, which is released by activated phagocytes." (PMID 31848284, 2019). "The early expression of S100 proteins during infection-induced inflammation suggests that S100A8 and S100A9 participate in innate immunity and mediate the inflammatory response." (PMID 29942307, 2018). "After infection with S. Typhimurium a marked increase of S100A8 and S100A9 expression was observed in liver and spleen but not at the local site of infection (colon)." (PMID 25860480, 2015). "Our studies have thus, underscored the role of a DAMP molecule (i.e. extracellular S100A9) in regulating virus-associated inflammation and uncovered a previously unknown function of the DDX21-TRIF-S100A9-TLR4-MyD88 signaling network in regulating inflammation during infection." (PMID 24391503, 2014). "Mice eventually controlled the infection, as indicated by a reduction in fungal burden, PMN number, S100a8 and S100a9 expression, calprotectin level and amelioration of inflammatory pathology at 21 and 42 dpi." (PMID 23853597, 2013). "Here we show that following HV-68 infection, serum levels of S100A8 or S100A9 increase during acute infection and are maintained during the establishment of viral latency." (PMID 22507226, 2012).
infection (continued). "This analysis also highlighted a central role for inflammation and infection, evidenced by networks containing genes such as CD74, S100A9, and THY1." (PMID 19513121, 2009). "To confirm whether the “detrimental” proteins enhanced SARS-CoV-2 infection, we conducted in vitro VeroE6 infection assays using purified recombinant VIM, SERPINC1, and S100A9 across the range of concentrations detected in the saliva." (PMID 38007005, 2024). "More specifically, the authors showed that S100A9 was elevated during chronic M. tuberculosis infection of C57BL/6 mice where it promotes neutrophil recruitment by CD11b, and C57BL/6 mice lacking S100A9 had lower M. tuberculosis CFU by 100 days post infection." (PMID 38861581, 2024). "At baseline, we found low levels of S100A9 protein in plasma and BALF of WT mice, which increased significantly in response to pneumococcal challenge with peak values observed at days 1–2 post-infection." (PMID 37467233, 2023). "We harvested the BALF from WT and S100a9 KO mice with and without infection and used flow cytometry to analyze cell phenotypes." (PMID 37624851, 2023). "Moreover, opposed to WT mice, S100A9 KO mice showed substantially increased BAL fluid levels of pro-inflammatory TNF-α and IL-1β and anti-inflammatory IL-10 on day 2 post-infection." (PMID 37467233, 2023). "After infection of Cas9-expressing ER-Hoxb8 precursor cells with CRISPR library lentiviral particles, the cells were differentiated for 3 days in the presence of GM-CSF to induce S100A8 and S100A9 expression." (PMID 35543413, 2022). "In contrast, S100A9 and CXCL2 expressions were already highly induced in uninfected wounds of WT mice at day 2 as well as day 7, and these levels were much more highly increased by infection." (PMID 36275755, 2022). "The authors found multiple alarmins (HMGB1, IL-33, S100A8, and S100A9) in the joint capsule of the FS patient group in amounts consistent with an infection, while in the control group they found no significant increase of infection related markers." (PMID 34046418, 2021). "Immunohistological stainings provide evidence that rather MDSC and not T cells are the main S100A8 and S100A9 producers early in infection; the absence of MDSC resulted in a reduced cardiac expression of S100A8+ immune cells." (PMID 34065891, 2021). "Relationship between plasma coagulation factor Vand S100A9 and spontaneous preterm birth ≤ 21 days of sampling or at < 34 weeks in women with preterm labor without infection and/or inflammation, analyzed by multiple logistic regression analysis." (PMID 34710180, 2021). "Treatment with FliC did not modulate the levels of S100A8 and S100A9 in both groups of mice at both 24 and 48h after infection." (PMID 33784296, 2021). "S100A8- and S100A9-expressing cells (see circles) were already present 4 dpi before CD3+ T lymphocytes (see circle) infiltrate the cardiac tissue, suggesting that not T cells but rather MDSC are the major S100A8 and S100A9 producers early in infection." (PMID 34065891, 2021). "Western blot results also demonstrated that the transfection of Rv1768 significantly suppressed p-P65 and p-IκBα expression compared to the empty vector group in both RAW264.7 2 h post-infection but not in S100A9–/– RAW264.7 cells." (PMID 32457723, 2020). "Our results showed that H37Rv infection inhibited both PGE2 production (****p < 0.0001) and Cox-2 expression in WT RAW264.7 cells 12 h post-infection, compared to those in S100A9–/– RAW264.7 cells." (PMID 32457723, 2020). "No such downregulation of S100A8 and S100A9 was observed by infection with UV-inactivated virus when compared with mock infected cells." (PMID 30677738, 2019). "InlC ubiquitination and binding to S100A9 occur at late stages of infection compared to InlC binding to the kinase IKK-α, an interaction that dampens the NF-κB-dependent inflammatory process at early stages of infection." (PMID 31848284, 2019).
infection (continued). "S100s, namely, S100A8, S100A9 and S100A12, have been recently recognized as newly discovered DAMPs that can activate the innate immune system in response to tissue injury and inflammation due to trauma, infection or cancer." (PMID 29795379, 2018). "Proteins S100A9, Heme peroxidase, LTF, Cathelicidin and PGLYRP1 were under-represented in TB+ animals when compared to uninfected TB- controls but protein levels increased as infection progressed in TB++ animals when compared to TB- and/or TB+ adult wild boar." (PMID 27027307, 2016). "Proteins S100a8 and S100a9 were among the most abundantly expressed under infection in both mouse strains, and completely absent in the control samples." (PMID 27490109, 2016). "Administration of anti-RAGE Ab (15 mg/kg i.p) on Day 4 and Day 7 post adeno-S100A9 infection of C57Bl/6 mice provided exposure to the lung, but had no impact on the cellular inflammation or the cytokines at Day 8 (data not shown)." (PMID 25706559, 2015). "In previous studies, we found that infection with HV-68 could induce the production of S100A8 and S100A9, and could also expand a population of CD11b+Gr-1+MDSCs in vivo." (PMID 22946998, 2012). "Here we questioned whether HV-68 infection of cultured, myeloid-derived macrophages and dendritic cells could result in the increased expression of S100A8 and S100A9." (PMID 22946998, 2012). "In vitro studies demonstrated that direct exposure of myeloid cells to HV-68 did not induce increased expression of S100A8 or S100A9 mRNAs or secreted protein regardless of the multiplicity of infection or time following infection." (PMID 22946998, 2012). "We found that the bacterial load in bladder or kidney homogenate of S100A9 KO mice was not significantly different from WT mice using 2 different bacterial doses at 2 different time points after infection." (PMID 20976233, 2010). "Further, a significant increase in nuclear S100A9 abundance was also observed in the amnion obtained from spontaneous preterm labor with no indication of infection (designated as preterm labor, PL) as compared to preterm elective cesarean section without labor (designated as preterm no labor, PNL)." (PMID 40171783, 2025). "However, on day 1 post-infection, multiple Ly6G/CD11b double-positive neutrophils were detected in the lung interstitium and alveolar air space of both WT and S100A9 KO mice with no apparent difference between groups." (PMID 37467233, 2023). "Furthermore, this phenotype is abolished in S100A9−/− mice, strongly suggesting that the interaction of S100A9 with native InlC could promote ROS production upon infection." (PMID 31848284, 2019). "However, S100A8/S100A9 response was found not to be critical for infection control in a murine model of UTI." (PMID 29145515, 2017). "We infected WT and S100A9-/- mice with 106 CFU viable S. Typhimurium and harvested MLN, blood, spleen and liver at predefined time points for quantitative cultures, seeking to collect data representative of local tissue defense, at the primary site of infection, and subsequent dissemination." (PMID 25860480, 2015). "Using S100A9 imaging, even the critical, initial activation of the phagocyte system in L. major-resistant C57BL/6 mice could be detected during the very early phase at day four after infection." (PMID 25098555, 2014). "S100A9 was released from undamaged IAV-infected cells and extracellular S100A9 acted as a critical host-derived molecular pattern to regulate inflammatory response outcome and disease during infection by exaggerating pro-inflammatory response, cell-death and virus pathogenesis." (PMID 24391503, 2014). "The ability of HV-68 infection to induce S100A8 and S100A9 production and to expand a population of CD11b+Gr-1+ cells suggested that increased numbers, or activity, of viral-expanded myeloid derived suppressor cells (MDSCs) might contribute to HV-68-associated metastatic breast cancer in this model." (PMID 22946998, 2012).
infection (continued). "To confirm that the failure to detect calprotectin in S100A9−/− mice is not due to insufficient tissue or a generalized diminished protein signal in these sections we analyzed the signal at m/z 5,679 whose abundance is not affected by infection." (PMID 23236280, 2012). "Here we report that S100A9 expression shows spontaneous (without detectable infection) and early (before 20 days of age) increased expression in lung neutrophils of both B6-CF and Bc-CF mice, in agreement with an approximate 3-fold increase in the number of resident neutrophils." (PMID 16571124, 2006). "However, since the biological activities of S100A8, S100A9, and S100A12 proteins are affected by redox conditions, pH, metabolite, and nutrient distribution at the site of infection, it is unclear whether the changes in protein expression are consistent with their biological activities yet." (PMID 38256103, 2024). "In addition, the type 1 IFN related genes (OAS1G, OAS2, OASL1, OASL2, S100A6, S100A8, S100A9, S100A11) that are necessary for activation of the inflammasome in Francisella novida-infected macrophages, were highly induced over the course of infection and peaked at 24 hpi." (PMID 21110886, 2010). "We observed that the gene expression of S100A9 and LY96 was increased in all patients, independent of infection days." (PMID 38262689, 2024). "During our studies to further understand how TLR response modulates expression/production of soluble secreted factors during infection, we found that cells lacking TLR adaptor TRIF failed to release S100A9 following IAV infection." (PMID 24391503, 2014). "Additional analysis of several cytokines (Tnf-α, Il-6, IL-1β, and IFN-γ) and antimicrobial factors (Reg3γ, S100a8, and S100a9) found to increase during RIMD infection showed a similar trend, i.e., they were also strongly induced by infection with POR1 or POR2 but not POR3." (PMID 31848276, 2019). "However, we show for the first time that S100A9 alone can directly activate TLR4 (in the absence of LPS) and contribute to the regulation of inflammation during infection with IAV, a non-LPS-expressing pathogen." (PMID 24391503, 2014). "IL-22-deficient mice were susceptible to C. albicans in the early but not late stages of infection, as indicated by signs of vaginal epithelial damage and inflammation, robust PMN recruitment, high S100a8 and S100a9 gene expression, calprotectin levels and fungal growth at 3 dpi." (PMID 23853597, 2013).